ARHGEF2 (Rho/Rac guanine nucleotide exchange factor 2)
Diseases named in the same sentence as ARHGEF2 in open-access papers (continued):
Sharing a sentence is not in itself a finding about the gene and the disease.
periodontitis (1 paper, 2024). An acute or chronic inflammatory process that affects the tissues that surround and support the teeth. "We also observed a significant increase in ARHGEF2 expression in periodontitis patients." (PMID 38491529, 2024). "An online differential expression analysis conducted using OralExplorer revealed several genes that were significantly upregulated in all six periodontitis-related datasets, including IL-1β, SRGN, CXCR1, FGR, ARHGEF2, and PTAFR." (PMID 38491529, 2024). "The analysis revealed simultaneous significant upregulation of IL1β, SRGN, CXCR1, FGR, ARHGEF2, and PTAFR in all six periodontitis-related datasets." (PMID 38491529, 2024).
tumor (36 papers, 2008 to 2025). "The result showed that, compared with the control group and the lenvatinib monotherapy group, the combination of the knockdown ARHGEF2 with lenvatinib achieved better tumor inhibition in vivo." (PMID 35896520, 2022). "According to the results from the TCGA database, ARHGEF2 was highly expressed in a variety of different tumor tissues." (PMID 35896520, 2022). "Animal experiments further demonstrated that the tumor sizes and weights of the ARHGEF2 group were obviously greater than those in the control group." (PMID 35896520, 2022). "The 22RV1 cells with the ARHGEF2 deletion exhibited profound attenuation of tumor growth relative to the control group." (PMID 36335093, 2022). "Cellular transformation by oncogenic RAS requires the RHO guanine exchange factor ARHGEF2 (also known as GEF-H1) for tumor growth and survival." (PMID 27835861, 2017). "ARHGEF2 plays an active role in tumor malignant progression." (PMID 35896520, 2022). "It thus may be anticipated that ARHGEF2 specific inhibitors can overcome the defect of lenvatinib in the anti-tumor therapy of ER stress-related apoptosis resistance." (PMID 35896520, 2022). "By inhibiting ARHGEF2, ER-stress-induced Lenvatinib resistance in tumor cells is reversed." (PMID 35896520, 2022). "However, the involvement of ARHGEF2 in tumor angiogenesis is uncertain up to now." (PMID 35896520, 2022). "In addition to the in vitro data, we examined the contribution of ARHGEF2 to tumor growth in vivo." (PMID 36335093, 2022). "Depletion of Arhgef2 (GEF-H1) and Arhgef17 (Tumour Endothelial Marker 4, TEM4) resulted in a reduced lamellipodia protrusion speed similar to that seen with TRPV4 inhibition." (PMID 40196692, 2025). "ARHGEF2 is important for the growth, lethal phenotype, and survival of CRPC cells and tumor xenografts." (PMID 38887275, 2024). "Elevated ARHGEF2 accelerates angiogenesis by modulating mRNA and the protein expression levels of EDN1, promoting HCC cell proliferation and tumor formation both in vitro and in vivo." (PMID 35896520, 2022). "Functionally, ARHGEF2 is important for the growth, lethal phenotype, and survival of CRPC cells and tumor xenografts." (PMID 36335093, 2022). "Elevated ARHGEF2 accelerates HCC angiogenesis via the EDN1 pathway, enhances HCC cell proliferation and tumor growth both in vitro and in vivo, and contributes to ER stress-related treatment resistance." (PMID 35896520, 2022). "However, mutations in RhoA are not frequent and accumulating evidence supports a role for its regulators including ARHGEF2 as well as the effectors ROCK1/2 and MLCK in tumor development and progression." (PMID 38970683, 2024). "In the study, we brought to light that ARHGEF2 was regulated by ER stress and marked up the invasion and migration abilities of HUVEC cells to promote angiogenesis and tumor growth, further participating in the resistance of HCC cells to molecularly targeted drugs mediated by ER stress." (PMID 35896520, 2022). "Our data suggest that the promoter regions of many RHOGEFs and RHOGAPs have similar potential transcriptional binding sites as ARHGEF2 and that RAS may regulate a complex network of RHO-GTPases that contribute to tumor survival, proliferation and metastatic phenotypes." (PMID 27835861, 2017). "We note that as opposed to Arhgef2−/− mice that behaved like controls, Rasal3−/− mice showed a significantly greater susceptibility to CA-CRC; this susceptibility was expressed both by an increase in the total number of tumors per colon, and an increase total tumor surface area." (PMID 38200184, 2024).
cancer (35 papers, 2015 to 2025). A tumor composed of atypical neoplastic, often pleomorphic cells that invade other tissues. "Both ARAP3 and ARHGEF2 have been associated with increased migration, invasion, and metastatic behavior in various cancer types." (PMID 38250802, 2023). "Finally, we found that cancer-associated ERK2 mutations had decreased activity in phosphorylating GEF-H1/ARHGEF2, a known ERK substrate harboring a WT-selective docking motif." (PMID 40015635, 2025). "Notably, one of the targets of miR-520f-3p, NEK9, is implicated in the phosphorylation of ARHGEF2, which, in turn, activates RhoA, promoting enhanced cell motility and facilitating both local and distant cancer cell spread." (PMID 39456519, 2024). "Genetic analyses uncovered a strong correlation between the level of ARHGEF2 expression and cancer progression and the development of drug resistance." (PMID 38970683, 2024). "As attested by the study, ARHGEF2 plays a key role in a variety of cancers by activating the RhoA signaling pathway, which may contribute to the proliferation and metastasis of cancer cells." (PMID 35896520, 2022). "Early studies identified ARHGEF2 as a RhoA-activating enzyme, despite the fact that ARHGEF2 has since been shown to play a crucial role in the invasion and metastasis of a variety of cancers." (PMID 35896520, 2022). "NEK9-medidated ARHGEF2 phosphorylation contributes to increased cell movement by inducing direct transformation of inactive RhoA to the active state to enable local invasiveness and distant metastasis of cancer cells." (PMID 33500736, 2021). "As expected, many apoptosis-related genes, involving ARHGEF2, TNFRSF12A, and SFRP2, were hypermethylated in CMT, and some oncogenes in human cancers, HRAS, FAM83H, and RET, were found as hypomethylated." (PMID 31569550, 2019). "Based on our findings that PKP4 is an important regulator of an ARHGEF2-RhoA-ROCK/MLCK signaling axis, it is tempting to speculate that this function of PKP4 may contribute to cancer." (PMID 38970683, 2024).
infection (8 papers, 2008 to 2025). The state of being infected such as from the introduction of a foreign agent such as serum, vaccine, antigenic substance or organism. "In human intestinal organoids, infection with Listeria monocytogenes selectively targets the junction-associated ARHGEF2–219 isoform, triggering an isoform switch to ARHGEF2-201 and induction of autophagy through interaction with STING and LC3." (PMID 41510227, 2025). "S. typhimurim grown to stationary phase, which resulted in the reduced expression of SPI-1, elicited similar amounts of IL-1β released from cultured WT and Arhgef2-/- BMDMs at 16-h post-infection." (PMID 32075101, 2020). "Together, these data indicate that Listeria selectively enhances transcription initiation at the ARHGEF2 P2 promoter, consistent with infection dependent induction of the short ARHGEF2 isoform during rapid activation of inflammatory and stress-response transcriptional programs." (PMID 41510227, 2025). "Moreover, WT and Arhgef2-/- BMDMs contained similar numbers of bacteria at 3-h post-infection." (PMID 32075101, 2020). "Immunoprecipitation of ARHGEF2 in human organoids before and after invasion with L. monocytogenes showed the interaction with autophagic protein complexes containing STING and LC3 that increased 8 hours post infection." (PMID 41510227, 2025).
neurodevelopmental disorder (2 papers, 2017 to 2018). A behavioral and cognitive disorder with onset during the developmental period that involves impaired or aberrant development of intellectual, motor, or social functions. "Our results highlight the crucial function of ARHGEF2 in human brain development and identify a mutation in ARHGEF2 as novel cause of a neurodevelopmental disorder." (PMID 28453519, 2017).
adenocarcinoma (1 paper, 2022). A common cancer characterized by the presence of malignant glandular cells. "To support the expression pattern of ARHGEF2 in NEPC, we detected the ARHGEF2 expression in the transgenic adenocarcinoma of mouse prostate (TRAMP) model." (PMID 36335093, 2022). "Expression of ARHGEF2 was also significantly increased in neuroendocrine differentiation CRPC (CRPC-NE) samples compared to CRPC with adenocarcinoma characteristics (CRPC-Adeno) samples." (PMID 36335093, 2022).
ARHGEF2 also shares sentences with these, for which no sentence is quoted: melanoma (4 papers); uveitis (4); bacterial infection (3); colon carcinoma (3); gastric cancer (2); acute lung injury (1); Alzheimer disease (1); atopic dermatitis (1); autoimmune uveitis (1); Breast Invasive Carcinoma (1); conjunctivitis (1); Crohn disease (1); cyst (1); diabetic retinopathy (1); E. coli infection (1); edema (1); endometriosis (1); endothelial dysfunction (1); familial Mediterranean fever (1); fibrosis (1); generalized epilepsy (1); glioblastoma (1); glioma (1); head and neck cancer (1); hyperimmunoglobulinemia D syndrome (1); inflammatory skin disease (1); injury (1); leukemia (1); lung adenocarcinoma (1); meningitis (1).
A further 16 diseases each share a sentence with ARHGEF2 in 1 paper.